IL2 (interleukin 2)
Diseases named in the same sentence as IL2 in open-access papers (continued):
Sharing a sentence is not in itself a finding about the gene and the disease.
Myalgia (5 papers, 2012 to 2020). "The one subject who reported moderate myalgias and injection site pain after vaccination displayed a distinctive, early cytokine response profile which included IL‐6, IL‐2, IL‐8, IP‐10, MCP‐1, TNF‐α, TARC, and MCP‐4." (PMID 28991404, 2018). "Polymyalgia rheumatica patients were shown to have a higher percentage of IL-2 and IFNγ producing CD4+ T cells in response to VZV stimulation using flow cytometry." (PMID 29118757, 2017). "Interestingly, arthralgia, myalgia and fatigue occurring at the time of study were associated with a higher proportion of CD8+ IFNγ and CD4+ IL-2-secreting cells, while headache was associated with higher CD4+ IL-2 and IFNγ ELISpot responses." (PMID 33679690, 2020). "Symptoms of arthralgia, myalgia, and fatigue occurring at the time of sampling were significantly associated with a higher proportion of CD8+ IFNγ and CD4+ interleukin (IL) 2–secreting cells, while headache was associated with higher CD4+ IL2 and IFNγ ELISpot response." (PMID 31784751, 2020). "Headache, fatigue, myalgia, and arthralgia were associated with the magnitude of T-cell response to pooled GP peptides, with higher CD4+ production of IL2 and CD8+ production of IFNγ, but not with antibody responses." (PMID 31784751, 2020).
nasopharyngeal carcinoma (5 papers, 2012 to 2025). A carcinoma arising from the nasopharyngeal epithelium. "In vitro, CAR-T cells exhibited cytolytic properties against EBV-positive nasopharyngeal carcinoma cells, in which LMP1 was overexpressed while producing interferon-γ (IFN-γ) and interleukin-2 (IL-2)." (PMID 40872284, 2025). "This study aims to investigate the correlation between serum levels of interleukin-2 (IL-2) and interferong (IFN-g) and the clinical prognosis of patients with nasopharyngeal carcinoma (NPC)." (PMID 38496017, 2024).
nephrotic syndrome (5 papers, 2014 to 2024). A collection of symptoms that include severe edema, proteinuria, and hypoalbuminemia; it is indicative of renal dysfunction. "Nephrotic syndrome is consistently associated with elevated levels of serum IL-2, IL-2R, IFN-γ, and TNF-α and normal levels of IL-1α, IL-1β, and IFN-α." (PMID 38127456, 2024). "The timing of IL2 infusions and the number of treatments were modified as well in consideration of the chronic nature of nephrotic syndrome unresponsive to drugs." (PMID 26413873, 2015). "We were unable to reproduce in humans the effects of IL2 described in rats and mice reducing de facto the interest on this drug in nephrotic syndrome." (PMID 26413873, 2015). "To evaluate a potential role of IL2 as Tregs inducer and proteinuria lowering agent in human nephrotic syndrome we treated 5 nephrotic patients with 6 monthly cycles of low-dose IL2 (1x106 U/m2 first month, 1.5x106 U/m2 following months)." (PMID 26413873, 2015). "Circulating levels of IL-2 and Tregs in nephrotic syndrome have been also investigated in the past in view of the general concept that nephrotic syndrome is a T cell disorder." (PMID 25343479, 2014). "Expansion of Tregs by low dose-IL2 could represent an alternative to cell therapy with Tregs infusion in patients with nephrotic syndrome refractory to all other treatments (i.e. steroids, calcineurin inhibitors, anti-CD20 monoclonal antibodies)." (PMID 26413873, 2015). "However, this pattern of interleukin-2 activity is felt to be part of a more widespread disorder of cellular immunity that results in nephrotic syndrome rather than being causal of proteinuria." (PMID 26573045, 2015). "The increase in Treg levels we obtained however did not result in reduction in urinary proteinuria indicating that IL2 does not modify the course of proteinuria in patients with nephrotic syndrome resistant to drugs in spite an evident increment of circulating Tregs." (PMID 26413873, 2015).
non-alcoholic steatohepatitis (5 papers, 2020 to 2022). "Increased IL-2 expression could also be shown in response to oxidative stress induced by stimulation with reactive oxygen species and free radicals, which is a common characteristic of chronic liver diseases such as non-alcoholic steatohepatitis (NASH)." (PMID 33187162, 2020).
ocular infection (5 papers, 2010 to 2025). "Our previous work demonstrated that ocular infection with a recombinant herpes simplex virus type 1 (HSV-1) expressing interleukin-2 (HSV-IL-2) causes CNS pathology, independently of macrophages in different mouse strains." (PMID 41248187, 2025). "In the first model, ocular infection of different strains of mice with a recombinant HSV-1 that expresses murine IL-2 constitutively (HSV-IL-2) causes CNS demyelination." (PMID 28542613, 2017). "The second model arose from the finding that ocular infection of macrophage-depleted mice with WT HSV-1 leads to demyelination in the absence of an external source of IL-2." (PMID 28542613, 2017).
peanut allergy (5 papers, 2021 to 2025). "In turn, IL-2 may be responsible for the increased plasma IL-5 in our allergic subjects, and successful oral immunotherapy for peanut allergy is associated with a decrease in both IL-5 and IL-2." (PMID 38067164, 2023). "Hypomethylation of the IL-2 gene was also found in children with peanut allergy, a finding that could explain their elevated levels of IL-2 when exposed to peanut proteins." (PMID 37927185, 2023).
plague (5 papers, 2013 to 2024). Plague is a severe bacterial infection caused by the gram-negative bacterium Yersinia pestis. "In macaques, HMBPP/IL-2 administration induced remarkable Vγ9Vδ2 T cell expansion and resulted in apparent attenuation of plague lesions in lung tissues caused by Yersinia pestis infection." (PMID 35924233, 2022). "Together, these findings indicate that compared to Alhydrogel only-formulated plague subunit vaccination, CpG 1826 and IL-2/GM-CSF cytokine-formulations drive improved long-lived antibody titers that persist at a memory timepoint." (PMID 36389793, 2022). "The Th1 immune response, in which cytokines like IFN-γ, TNF-α, and IL-2 play important roles, is necessary for plague prevention." (PMID 33014895, 2020). "In contrast, mice immunized with plague antigens formulated with either Alhydrogel-bound CpG 1826 or IL-2/GM-CSF cytokines exhibited dramatic increases in their F1V, V, and F1-specific antibody titers that were higher than the Alhydrogel only-formulated vaccine groups." (PMID 36389793, 2022). "Notably, compared to the EV76-immunized group, EV76Δyp2-immunized mice exhibited a significantly higher secretion level of Th1-related cytokines, including TNF-α, IL-2, and IL-12p70, which have been recognized as crucial factors in conferring protection against plague." (PMID 38547321, 2024). "In this study, we immunized mice with recombinant plague antigens formulated with several types of adjuvants including Alhydrogel, Alhydrogel combined with CpG ODN 1826, and Alhydrogel combined with IL-2 + GM-CSF." (PMID 36389793, 2022).
prostate tumor (5 papers, 2015 to 2022). "Again, a slightly but significantly positive correlation between TRIM66 and IL‐2 was observed in the clinical prostate tumor database (P < 0.01), which was consolidated by the down‐regulation of IL‐2 at both transcript and protein levels in TRIM66‐deficient PC‐3 cells." (PMID 31981447, 2020).
pulmonary arterial hypertension (5 papers, 2020 to 2025). Pulmonary arterial hypertension (PAH) is a group of diseases characterized by mean pulmonary artery pressure >20 mmHg and elevated pulmonary arterial resistance leading to right heart failure. "The Nef constructs derived from HIV-pulmonary hypertensive donors demonstrated significant increases in Th1 cytokines IL-2, IL-12p70, and IFNg, as well as anti-inflammatory IL-10, but did not elicit innate immunity cytokines IL-1b or TNFa." (PMID 40559196, 2025). "Studies have also confirmed that IL-2 is involved in the pathogenesis of IPAH, as it increases the expression of endothelin associated with the development of pulmonary hypertension." (PMID 37761997, 2023). "Additional researches have also indicated that IL-2 increases the expression of endothelin, which accompanies the development of pulmonary hypertension." (PMID 34442052, 2021). "Additionally, IL-2 has been found to promote vasoconstriction and pulmonary hypertension." (PMID 37761997, 2023).
respiratory infection (5 papers, 2010 to 2025). "IL-2 (−330) SNP is known to increase the risk for respiratory infections." (PMID 24718616, 2014). "Mice treated with IL-2 exhibited reduced illness and improved antibody responses, suggesting that IL-2 could serve as an adjuvant in vaccines or immune therapies for respiratory infections." (PMID 40407543, 2025). "Although these SAEs were classified as possibly related, the patient also had an intercurrent respiratory infection, and the IL-2 mutein inflammatory response could have exacerbated the immunopathology." (PMID 40486521, 2025). "Induction of IL-10+ CD8 T cells by CD4 T cell-derived IL-2 may thus act as further layer of buffering against damaging inflammation during respiratory infections." (PMID 31412088, 2019). "However, that we found a stronger impact of IL-2 on inflammation in the lung than in the serum, even when IL-2 was administered systemically, suggests the lung and responses against respiratory infections may be particularly sensitive to IL-2." (PMID 31412088, 2019). "Furthermore, we stress that while IL-2 production can be boosted or restored by the systemic blockade of checkpoint inhibitors, how production of IL-2 by T cells responding to respiratory infection impacts patient outcome in such settings, including cancer therapy, remains to be determined." (PMID 31412088, 2019).
severe combined immunodeficiency (5 papers, 2022 to 2024). Severe combined immunodeficiency (SCID) comprises a group of rare monogenic primary immunodeficiency disorders characterized by a lack of functional peripheral T lymphocytes resulting in early-onset severe respiratory infections and failure to thrive. "JAK3 knock-out mice are found to develop severe combined immunodeficiency (SCID) due to impairment in B cell development associated with IL-2, IL-4, IL-7, IL-9, and IL-15 receptor signaling." (PMID 38380328, 2024). "They include genetically modified mice, such as interferon gamma receptor knockout (IFN-γR-KO), interferon gamma knockout (IFN-γ-KO), interleukin 2 knockout (IL-2-KO), and severe combined immunodeficiency (SCID) mice (8, –, 11)." (PMID 35735982, 2022). "In this study, we report a 4-month-old boy with T−B+NK− severe combined immunodeficiency (SCID) due to a novel mutation in exon 2 of IL2RG, the gene encoding the interleukin (IL) common gamma chain (γc) of the cytokine receptors for IL-2, IL-4, IL-7, IL-9, IL-15, and IL-21." (PMID 35498802, 2022).
Sézary syndrome (5 papers, 2006 to 2020). "Cutaneous lesions of MF are characterised by an epidermal Th1-type cytokine profile consisting of interleukin-2 and IFN-γ, whereas a type 2 cytokine production profile, consisting of IL-4, is more likely to occur in Sézary syndrome, the erythrodermic variant of MF." (PMID 16495924, 2006). "IL-2-dependent T-cell lines infected with HTLV-1 were also established from a patient with HAM/TSP, a Sézary syndrome-like skin disease with HTLV-1-infection, and two healthy carriers of HTLV-1." (PMID 32210945, 2020). "Both, IL-2 and IL-15 reportedly promote growth and viability of CTCL and Sézary syndrome derived cell lines, while co-expression of IL-15 and IL-17F characterizes mycoses fungoides." (PMID 27144517, 2016).
thyroid cancer (5 papers, 2018 to 2025). "Serum IL-2 has been shown to discriminate patients with active thyroid cancer from the healthy with a sensitivity of 98%, and specificity of 58%." (PMID 32324757, 2020). "The TSH‐CAR‐T cells demonstrate effective antitumor activity against TSHR‐positive differentiated thyroid cancer (DTC) cell lines in vitro, accompanied by cytokine release (IFNγ, IL‐2) and robust proliferation." (PMID 40985353, 2025). "Additionally, interleukin-2 (IL-2), a multifunctional cytokine is known to activate T cells in TME of thyroid cancer by upregulating Human Leukocyte antigen (HLA) class I molecule expression and subsequent tumor antigen presentation." (PMID 37563607, 2023).
ulcer (5 papers, 2012 to 2026). "This study aimed to evaluate its clinical effectiveness in either gel in orabase or mouthwash, on pain reduction, ulcer healing, recurrence rates, and salivary IL-2 level in patients with RAS." (PMID 41851196, 2026). "When compared to a placebo, both EPO formulations significantly decreased pain, ulcer size, and salivary IL-2 levels (p < 0.001)." (PMID 41851196, 2026). "EFAM significantly decreased tumor necrosis factor-alpha (TNF-α) and interleukin-2 (IL-2) by 36.4% and 50.8%, respectively, in the ulcer tissues while, CEAM and BFAM exhibited lower activity at the same dose." (PMID 35161436, 2022). "IL-2 expression in granulation tissue of chronic ulcer wounds was positively proportional to the number of new capillaries, which significantly promoted ulcer healing." (PMID 36016687, 2022). "Various cytokines may contribute to the pathogenesis of ulcers, as elevated IL-2, IFN-γ, and TNF-α, while lower concentrations of IL-10 were reported in lesions of RAS patients." (PMID 23258985, 2012). "In comparison with the control group, IND-treated rats showed visible multiple ulcers with ulcer index, serum MDA, IL-2 and IL-6 were elevated while IL-10, PGE2, NO, and eNOS mRNA expression were significantly reduced." (PMID 33833690, 2021).
upper respiratory tract infection (5 papers, 2016 to 2025). "Since upper respiratory tract infection was the most common form of infection in our human study, we next evaluated the effect of Ld-IL2 therapy in a mouse model of influenza virus infection that also mimics local infection." (PMID 34618873, 2021). "s 25.1% in non-IL-2 group) decrease of total infection incidence in the IL-2 group, especially in herpes and upper respiratory tract infection." (PMID 34618873, 2021). "This study aimed to determine the phenotype of T cells and IL-2 expression in children suffering from upper respiratory tract infection with Streptococcus pyogenes (S. pyogenes)." (PMID 27493590, 2016). "For this purpose, IL-2 expression at its gene and protein levels and quantitation of CD4+ and CD8+ T lymphocytes were assessed in children aged 0-5 years old suffering from upper respiratory tract infection with S. pyogenes and healthy children of the same age." (PMID 27493590, 2016).
vitamin D deficiency (5 papers, 2021 to 2025). A nutritional condition produced by a deficiency of VITAMIN D in the diet, insufficient production of vitamin D in the skin, inadequate absorption of vitamin D from the diet, or abnormal conversion of vitamin D to its bioactive metabolites. "Our data highlight the specific regulation of the IL-2/STAT5 pathway by vitamin D. Vitamin D deficiency and impaired Vdr signaling caused elevated IL-2 production by Th2 cells, leading to high IL-13 production." (PMID 38567749, 2024). "Elevated TNF-α, INF-γ, IL-1β, and IL-2 levels have been observed in patients with vitamin D deficiency." (PMID 34281061, 2021). "Elevated inflammatory markers, including neutrophil and monocyte counts, as well as pro-inflammatory cytokines, such as IL-2 and IL-8, have been associated with low serum 25(OH)D concentrations, reinforcing the link between inflammation and vitamin D deficiency." (PMID 41180246, 2025).
X-linked severe combined immunodeficiency (5 papers, 2014 to 2024). "X-linked severe combined immunodeficiency (SCID-X1 or XSCID) is caused by mutations in IL2RG gene which encodes the common cytokine gamma chain (γc) subunit shared by multiple cytokine receptors (interleukin (IL)-2, 4, 7, 9, 15 and 21)." (PMID 36685559, 2022). "X-linked severe combined immunodeficiency (XSCID) is caused by a genetic mutation within the common gamma chain (γc), an essential component of the cytokine receptors for interleukin (IL)-2, IL-4, IL-7, IL-9, IL-15, and IL-21." (PMID 25025687, 2014). "X-linked severe combined immunodeficiency (X-SCID) is caused by mutations of IL2RG, the gene encoding the interleukin common gamma chain (IL-2Rγ or γc) of cytokine receptors for interleukin (IL)-2, IL-4, IL-7, IL-9, IL-15, and IL-21." (PMID 34248995, 2021). "The similarity of IL-21 to IL-2, IL-4, and IL-15, suggests the possibility that IL-21 might share an important receptor on the common cytokine receptor γ chain (γc), encoded by IL2RG, the gene found to be mutated in humans with X-linked severe combined immunodeficiency (XSCID)." (PMID 33924897, 2021).
adult T cell leukemia (4 papers, 2011 to 2025). "Human T-cell leukemia virus type 1 (HTLV-1), an etiological agent of adult T-cell leukemia, immortalizes and transforms primary human T cells in vitro in both an interleukin (IL)-2-dependent and IL-2-independent manner." (PMID 25175936, 2014). "In vitro, activation of the IL-2 and IL-2 receptor promoters is mediated by cellular transfection of human T-cell leukemia virus type I (HTLV-I), a pathogenic factor in human adult T-cell leukemia/lymphoma (ATLL)." (PMID 23675235, 2011). "To identify the genes whose expression might positively or negatively regulate IL-2 signaling, we performed a genome-wide CRISPR knockout screening using an IL-2–responsive cell line, ED40515(+), derived from a patient with adult T cell leukemia (ATL)." (PMID 40680114, 2025). "To identify regulators of IL-2 signaling, we performed genome-wide CRISPR-knockout screening in IL-2–dependent cells derived from a patient with adult T cell leukemia (ATL) and found enrichment of single guide RNAs targeting PRDM1, which encodes B lymphocyte–induced maturation protein 1 (BLIMP1)." (PMID 40680114, 2025).
anxiety disorder (4 papers, 2013 to 2024). A category of psychiatric disorders which are characterized by anxious feelings or fear often accompanied by physical symptoms associated with anxiety. "In individuals with current depressive or anxiety disorders compared to healthy controls, elevated levels were observed in CRP, IL-6, IL-8, IL-18, MCP-1, MIP-1α, MIP-1β, MMP2, and TNF-β, while TNF-α, IL-10, IFN-γ, IL-2, and IL-4 levels either showed no significant elevation or were lower." (PMID 39273641, 2024).
autoimmune uveitis (4 papers, 2021 to 2024). An autoimmune form of uveitis (disease). "Studies have implicated IL-2 and IL-2Rα in autoimmune uveitis pathogenesis through the modulation of pathogenic Th17 cells, though detailed mechanisms remain under investigation." (PMID 39239046, 2024). "Future studies are required to further study how IL‐2 is involved in the modulation of the balance of Treg cells and pathogenic pro‐inflammatory Tem cells in autoimmune uveitis." (PMID 37720629, 2023). "It is worth noting that IL-2, IL-6, IL-13, IL-18, IFN-γ, and TNF-α were significantly higher in the aqueous humor of children with JIA-associated autoimmune uveitis." (PMID 36969183, 2023).
autoimmune vasculitis (4 papers, 2016 to 2022). An autoimmune form of vasculitis. "Of note, short-term low-dose IL-2 administration induces variable Treg cell expansion in T1D22, 23 and autoimmune vasculitis patients." (PMID 27708334, 2016).
bacterial meningitis (4 papers, 2013 to 2024). Inflammation of the membranes surrounding the brain and spinal cord due to a bacterial infection. "Cytokines IL-2, IL-17A, and the chemokine MIP-3α (CCL20) have also been shown to be associated with bacterial meningitis and promote BBB disruption (46, –, 49)." (PMID 39400158, 2024). "Still, we could not distinguish enteroviral meningitis from bacterial meningitis with the parameters of CSF cytokines IL‐2, IL‐6, IL‐10, TNF, and IFN‐γ." (PMID 31912935, 2020). "Thus, we could not distinguish enteroviral meningitis from bacterial meningitis with the parameters of CSF cytokines IL‐2, IL‐6, IL‐10, TNF, and IFN‐γ." (PMID 31912935, 2020).